ZBP1 (Z-DNA binding protein 1)
Diseases named in the same sentence as ZBP1 in open-access papers (continued):
Sharing a sentence is not in itself a finding about the gene and the disease.
H1N1 virus infection (2 papers, 2024 to 2025). "In contrast, ZBP1 deficiency, which prevents cell death but promotes virus replication, does not protect mice from lethal H1N1 virus infections." (PMID 39811662, 2025). "RIPK1 knockout did not significantly change the level of ZBP1 expression in the clone used here in the absence or presence of H1N1 virus infection at multiple time points." (PMID 39044278, 2024).
heart failure (2 papers, 2022 to 2025). Inability of the heart to pump blood at an adequate rate to meet tissue metabolic requirements. "In addition to the CGAS-STING1 axis, the Z-DNA binding protein 1, which is up-regulated in mouse models of heart failure and promotes PANoptosis, is also implicated in the cardiotoxicity of doxorubicin." (PMID 40180542, 2025).
herpesvirus infection (2 papers, 2018 to 2019). "Altogether, ZBP1-dependent restriction of herpesvirus infection emerges as a potent antiviral armament of the innate immune system." (PMID 30050136, 2018). "Taken together, our findings expand the relevance of ZBP1 as a sensor of herpesvirus infection in mammals." (PMID 30050136, 2018).
injury (2 papers, 2023 to 2025). Damage inflicted on the body as the direct or indirect result of an external force, with or without disruption of structural continuity. "More importantly, selective knockdown of S1pr2, Zbp1 or Mlkl in macrophage decreased ZBP1/p-MLKL-mediated necroptosis, and further attenuated liver fibrosis in BDL-induced cholestatic liver injury." (PMID 36859525, 2023).
lung carcinoma (2 papers, 2021 to 2024). "Based on our research findings, we have identified a correlation between methylation of cg09897064 and decreased expression of ZBP1, indicating a link to unfavorable prognosis in patients with lung cancer." (PMID 38369516, 2024). "Our research has identified cg09897064 methylation and reduced expression of ZBP1 as adverse prognostic factors in lung cancer patients." (PMID 38369516, 2024). "Our research has unveiled that cg09897064 methylation and reduced expression of ZBP1 serve as adverse prognostic factors in lung cancer patients." (PMID 38369516, 2024).
lung disease (2 papers, 2010 to 2021). "By specific lung cell isolation, several interferon-related and autoimmune genes were disproportionately expressed among CIA and CIA+ODE (e.g. Oasl1, Oas2, Ifit3, Gbp2, Ifi44, and Zbp1), corresponding to RA and RA-associated lung disease." (PMID 33577605, 2021).
lupus nephritis (2 papers, 2013 to 2025). Glomerulonephritis in the context of systemic lupus erythematosus. "In lupus nephritis (LN), ZBP1 expression is upregulated in the kidneys, and ZBP1-mediated PANoptosis serves as a critical mechanism underlying renal injury." (PMID 41583472, 2025).
multiple myeloma (2 papers, 2023 to 2025). "In contrast, in multiple myeloma, ZBP1 activates IRF3 that, together with IRF4, promotes expression of cell cycle genes and thereby facilitates proliferation of malignant cells." (PMID 37450010, 2023).
neuroblastoma (2 papers, 2012 to 2013). Neuroblastoma (NB) is the most common solid, extracranial childhood tumor. "Knock-down of mouse KSRP (mZBP2) using siRNAs blocked the initial outgrowth of neurites 12 hours after inducing differentiation of a mouse neuroblastoma cell line, presumably due to decreased loading of ZBP1 onto β-actin mRNA." (PMID 24244461, 2013). "This showed that there was an accumulation of β-actin mRNA in the growth cones of neurons expressing GFP-RACK1Y246F, probably as a consequence of an impaired release from Flag-ZBP1, as observed neuroblastoma cells." (PMID 22523568, 2012). "Ribosomal profiles were conducted on neuroblastoma cells co-expressing Flag-ZBP1 with GFP, GFP-RACK1wt or with GFP-RACK1Y246F cDNAs." (PMID 22523568, 2012). "The results in neuroblastoma cells indicate that the decrease of the binding of β-actin mRNA/ZBP1 complex to GFP-RACK1Y246F on ribosomes reduces the release of β-actin mRNA from ZBP1 and, consequently, its translation." (PMID 22523568, 2012). "Thus, the results from growth cones of cortical cells, as well as in neuroblastoma cells indicated that, the release from Flag-ZBP1 and the translation of β-actin mRNA were inhibited by GFP-RACK1Y246F.over-expression." (PMID 22523568, 2012).
psoriasis (2 papers, 2020 to 2023). An autoimmune condition characterized by red, well-delineated plaques with silvery scales that are usually on the extensor surfaces and scalp. "ZBP1 is a cytosolic DNA sensor mediating necroptosis induced by IFN-β and IFN-γ37, which are highly expressed in psoriasis." (PMID 32075957, 2020).
acute lung injury (1 paper, 2025). A condition of lung damage that is characterized by bilateral pulmonary infiltrates (pulmonary edema) rich in neutrophils, and in the absence of clinical heart failure. "Acute lung injury (ALI), characterized by excessive inflammation and cell death, is closely associated with ZBP1-mediated PANoptosis, a programmed cell death mechanism." (PMID 41479902, 2025).
adenovirus infection (1 paper, 2022). "The authors also followed the role of ZBP1/DAI and p204/Ifi-204 in the IFN responses and found that the overexpression or knockout of ZBP1/DAI or p204/Ifi-204 had no impact in the IFN responses to adenovirus infection." (PMID 35458396, 2022).
AIDS (1 paper, 2022). A syndrome resulting from the acquired deficiency of cellular immunity caused by the human immunodeficiency virus (HIV). "In addition, our study also indicated a putative role for novel mediators of HIV-1 immunity, namely ZBP1, LAMP3, CXCL10, LGALS9, and ANKYF1, all of which have been associated with HIV-1/AIDS disease progression." (PMID 35333911, 2022).
atherosclerosis (1 paper, 2021). A disease characterized by the build-up of fatty material and calcium deposition in the arterial wall resulting in partial or complete occlusion of the arterial lumen. "Overlap of the three protein coding genes (and protein names) with atherosclerosis in PubMed yielded 1 hit for Zbp1, 9 hits for Pck1, and 0 hits for Pmepa1." (PMID 35052410, 2021).
autism spectrum disorder (1 paper, 2025). A spectrum of developmental disorders that includes autism, and Asperger syndrome. "IMP1/ZBP1 has been reported to bind several mRNAs encoded by autism spectrum disorder genes, and our findings indicate that limiting IMP1/ZBP1 availability disrupts mRNA localization to PeMPs and leads to dysfunctional microglia." (PMID 41212909, 2025).
bacterial sepsis (1 paper, 2023). "Nucleic acid sensors with particular relevance to bacterial sepsis include the cGAS-STING pathway, Toll-like receptor (TLR) 9, and z-DNA binding protein 1 (ZBP1)." (PMID 38274794, 2023).
bladder cancer (1 paper, 2022). "In bladder cancer cells, ABT-737 induces cell necrosis when either ZBP1 or RIPK3 are knocked down, which is achieved by upregulating the interaction between ZBP1 and RIPK3." (PMID 36615244, 2022).
breast tumors (1 paper, 2023). "ZBP1, overexpressed in necrotic breast tumors, has been linked to the induction of interferon." (PMID 38111587, 2023).
cardiomyopathy (1 paper, 2025). A disease of the heart muscle or myocardium proper. "Cooperative interactions between CGAS and ZBP1 induce type I interferon response and activate the cell death programs in myocardial disease, including in doxorubicin-induced cardiomyopathy." (PMID 40180542, 2025).
Cholestatic liver disease (1 paper, 2023). "Our results help in better understanding the role of GDCA/S1PR2/ZBP1/p-MLKL mediated macrophage necroptosis in cholestatic liver diseases, and might provide novel therapeutic strategies to attenuate BA liver fibrosis." (PMID 36859525, 2023).
colorectal adenocarcinoma (1 paper, 2025). The most common type of colorectal carcinoma. "The interaction of RHIM with ZBP1 sequesters ZBP1 into decoy amyloid assemblies and prevents ZBP1-driven apoptosis during a varicella zoster virus infection of the human colorectal adenocarcinoma cell line, HT-29." (PMID 40006996, 2025).
Constipation (1 paper, 2025). Infrequent or difficult evacuation of feces. "This study shows that MLKL and its upstream regulatory molecule ZBP1 expression increases in the constipation model, suggesting a potential backup death mechanism triggered by microenvironmental stress, such as inflammation or cytokine stimulation." (PMID 41050658, 2025).
co‐infection (1 paper, 2025). "Given the shared capacity of IAV and coronavirus to trigger ZBP1‐mediated cell death, we next investigated IAV replication and pulmonary inflammatory responses in ZBP1‐deficient (KO) mice after co‐infection of IAV and MHV at day 3 post‐IAV infection." (PMID 40810650, 2025). "MHV co‐infection in ZBP1‐deficient mice synergistically amplified Il6 and Tnf expression, whereas Il1b, Cxcl1, and Cxcl5 levels remained refractory to further elevation." (PMID 40810650, 2025). "Notably, ZBP1 KO mice exhibited exacerbated pulmonary inflammation following IAV challenge, with co‐infection differentially modulating cytokine responses." (PMID 40810650, 2025). "Furthermore, type I interferon pathway activation was potentiated in ZBP1 KO lungs post‐IAV infection, with MHV co‐infection exhibiting additive effects on this signaling axis." (PMID 40810650, 2025).
craniosynostosis (1 paper, 2022). Craniosynostosis is defined as the premature fusion of one or more cranial sutures leading to secondary distortion of skull shape resulting in skull deformities with a variable presentation. "ZBP1 depletion inhibits the expression of RUNX2 and AXIN2, both genes associated with craniosynostosis." (PMID 35627201, 2022).
Crohn's colitis (1 paper, 2025). Crohn's disease affecting the colon. "This study elucidates a pathogenic pathway in which ITLN1 competitively binds TRIM8 to inhibit CAPN2 ubiquitination and degradation, stabilizing CAPN2 to promote ZBP1-mediated PANoptosis in IECs and exacerbate Crohn's colitis." (PMID 40520022, 2025). "This induces ZBP1-mediated PANoptosis in IECs, resulting in impaired intestinal mucosal barrier function and the release of a substantial number of inflammatory cytokines, promoting the progression of Crohn's colitis." (PMID 40520022, 2025).
dyschromatosis symmetrica hereditaria (1 paper, 2022). Acropigmentation of Dohi is a genodermatosis characterized by the presence of hyperpigmented and hypopigmented macules, principally located on the extremities and limbs. "For example, in Dyschromatosis Symmetrica Hereditaria, pigmentation loss in the skin may follow from ZBP1-induced melanocyte cell death, with the threshold for ZBP1 activation lowered by ADAR1 haploinsufficiency present in this disorder." (PMID 35328502, 2022).
E. coli infection (1 paper, 2025). "We further demonstrated that double-stranded RNA (dsRNA) and ZBP1 mediated neutrophil necroptosis and exacerbated pulmonary E. coli infection." (PMID 40359428, 2025). "To confirm the role of ZBP1 in mediating neutrophil necroptosis in vivo, we conducted pulmonary E. coli infection in Zbp1-/- mice." (PMID 40359428, 2025). "This interaction suggests that ZBP1 plays a direct role in mediating neutrophil necroptosis during pulmonary E. coli infection." (PMID 40359428, 2025). "To determine whether dsRNA is involved in neutrophil necroptosis, we performed IP analysis and found that ZBP1 binds dsRNA in BALF neutrophils upon E. coli infection." (PMID 40359428, 2025). "Moreover, blocking dsRNA or depleting ZBP1 ameliorated the pathophysiological process of pulmonary E. coli infection." (PMID 40359428, 2025). "We then investigated whether TRIF and ZBP1 mediate neutrophil necroptosis upon E. coli infection." (PMID 40359428, 2025). "Importantly, compared with their Zbp1+/+ littermates, Zbp1-/- mice presented a significantly lower pulmonary bacterial burden and decreased lung injury, similar to the effects observed in mice treated with the dsRNA antibody during pulmonary E. coli infection." (PMID 40359428, 2025). "RNA-seq analysis revealed that ZBP1 transcripts were abundant in BALF neutrophils from both Casp1+/+ and Casp1-/- mice following pulmonary E. coli infection, whereas TRIF transcripts were not detectable." (PMID 40359428, 2025).
epilepsy (1 paper, 2024). A brain disorder characterized by episodes of abnormally increased neuronal discharge resulting in transient episodes of sensory or motor neurological dysfunction, or psychic dysfunction. "In this study, we then assessed the mRNA of ZBP1, GSDMD, and RIPK1 and the protein expression of ZBP1 and RIPK1 in epilepsy models in vitro." (PMID 38404827, 2024). "We also conducted various experiments to validate the expression changes of three PANoptosis markers (ZBP1, GSDMD, and RIPK1) during the pathophysiological process of epilepsy." (PMID 38404827, 2024). "Our results confirmed changes in ZBP1, GSDMD, and RIPK1 expression during epilepsy onset, further supporting the potential involvement of PANoptosis in seizure pathogenesis." (PMID 38404827, 2024). "Additionally, we assessed the mRNA of ZBP1, GSDMD, and RIPK1 and the protein expression of ZBP1 and RIPK1 in epilepsy models in vitro." (PMID 38404827, 2024). "We observed a significant increase in the mRNA expression of ZBP1, GSDMD, and RIPK1 in the peripheral blood of newly diagnosed seizure patients compared to age-matched healthy children (P < 0.01), suggesting their involvement in epilepsy onset." (PMID 38404827, 2024).
epithelial dysplasia (1 paper, 2025). "In the 4NQO model, Zbp1−/− mice predominantly developed mild-to-moderate epithelial dysplasia, whereas WT mice uniformly progressed to invasive carcinoma." (PMID 41430036, 2025).
Flavivirus Infections (1 paper, 2024). Infections with viruses of the genus FLAVIVIRUS, family FLAVIVIRIDAE. "During flavivirus infections, ZBP1 acts as a protective factor and is significantly increased in the brain of mice infected with Zika Virus or West Nile Virus (WNV)." (PMID 39475237, 2024).
helminth infection (1 paper, 2025). "We propose for the first time that Zbp1 participates in the immune response to helminth infection." (PMID 39853924, 2025).
intrahepatic cholangiocarcinoma (1 paper, 2025). A carcinoma that arises from the intrahepatic bile duct epithelium in any site of the intrahepatic biliary tree. "In intrahepatic cholangiocarcinoma (ICC), mouse models have demonstrated that ZBP1 deficiency suppresses PANoptosis." (PMID 41583472, 2025).
ischemic disease (1 paper, 2025). Lack of blood supply to an area of the body, resulting in impairment of tissue oxygenation. "We found that extracellular dsRNA and ZBP1-regulated neutrophil necroptosis could be potential targets for the treatment of these cell death-related diseases, including infectious diseases, cancer, neurological diseases, ischemic diseases and cardiovascular diseases." (PMID 40359428, 2025).
Jaundice (1 paper, 2023). Yellow pigmentation of the skin due to bilirubin, which in turn is the result of increased bilirubin concentration in the bloodstream. "More importantly, the mRNA expression of ZBP1 in liver tissues was correlated with jaundice clearance after Kasai surgery at six months (one of the important prognostic factors of BA), while ZBP1 expression was significantly increased in the non-jaundice-free patients." (PMID 36859525, 2023).
laryngeal carcinoma (1 paper, 2024). Carcinoma that arises from the laryngeal epithelium. "lncRNA FLJ20021 is highly expressed in cisplatin-resistant laryngeal cancer cells, and silencing lncRNA FLJ20021 plays a positive role in overcoming cisplatin-resistant laryngeal cancer by regulating CDK1 and mediating PANoptosis in a ZBP1-dependent manner." (PMID 38967843, 2024). "This study suggests that targeting lncRNA FLJ20021 can be a promising approach to combat cisplatin resistance in laryngeal cancer by regulating CDK1 and promoting PANoptosis via the ZBP1 pathway." (PMID 38967843, 2024).
liver cancer (1 paper, 2025). An epithelial or non-epithelial malignant neoplasm that arises from the liver. "Collectively, these findings indicate that KLX induced PANoptosis in liver cancer cells by upregulating ZBP1 expression at both the RNA and protein levels." (PMID 40148674, 2025). "Collectively, these findings suggest that ZBP1 overexpression inhibited both the proliferation and migration of liver cancer cells." (PMID 40148674, 2025). "To assess the impact of ZBP1 on liver cancer cells, we overexpressed ZBP1 with a plasmid, and confirmed the overexpression efficiency via Western blot analysis." (PMID 40148674, 2025). "This study is the first to report the direct role of ZBP1 in liver cancer, highlighting its ability to promote liver cancer cell death via PANoptosis." (PMID 40148674, 2025). "Previous studies have shown that ZBP1 knockdown reduces the efficacy of small molecules against liver cancer." (PMID 40148674, 2025). "This upregulation of the PANoptosome component ZBP1 triggered PANoptosis, ultimately promoting liver cancer cell death." (PMID 40148674, 2025). "Elevated ZBP1 levels significantly suppressed liver cancer cell proliferation and migration, whereas the inhibitory effects of KLX were reversed upon ZBP1 knockdown." (PMID 40148674, 2025). "Here, we found that KLX increased HOXD10 levels, which in turn promoted ZBP1 transcription and inhibited liver cancer cell growth." (PMID 40148674, 2025). "In this study, we found that KLX promoted PANoptosis in liver cancer cells via ZBP1, effectively inhibiting cancer cell proliferation and migration." (PMID 40148674, 2025). "In conclusion, KLX promoted PANoptosis in liver cancer cells by upregulating ZBP1 and preventing its degradation, thereby inhibiting liver cancer progression and migration." (PMID 40148674, 2025). "To determine whether the suppressive effects of KLX on liver cancer were mediated through ZBP1, we effectively silenced ZBP1 expression with siRNA." (PMID 40148674, 2025). "However, the specific effects of ZBP1 on liver cancer cell proliferation and migration remain unexplored." (PMID 40148674, 2025). "Notably, we identified for the first time the function of ZBP1 in liver cancer cells and demonstrated that KLX increased ZBP1 stability by changing its spatial conformation, which prevented its ubiquitination and subsequent degradation." (PMID 40148674, 2025).
liver disease (1 paper, 2025). "Targeting the ERV/Zbp1 pathway may offer new therapies for patients with alcohol-associated liver disease." (PMID 40359032, 2025). "To further support the importance of intestinal rather than hepatic Zbp1 in mediating the effect on ethanol-induced liver disease, we generated mice with specific deletions of Zbp1 in Kupffer cells (Zbp1ΔKC) and hepatocytes (Zbp1ΔHep)." (PMID 40359032, 2025). "And indeed, bacterial translocation and ethanol-induced liver disease are reduced by either suppression of ERVs using antiretrovirals or elimination of Zbp1 in IECs." (PMID 40359032, 2025). "Taken together, these findings demonstrate the critical role of intestinal epithelial Zbp1 in ethanol-induced liver disease." (PMID 40359032, 2025). "Mice lacking Zbp1 in IECs are protected from ethanol-induced liver disease." (PMID 40359032, 2025).